DRAM1 (DNA damage regulated autophagy modulator 1)
Diseases named in the same sentence as DRAM1 in open-access papers (continued):
Sharing a sentence is not in itself a finding about the gene and the disease.
diabetic retinopathy (1 paper, 2025). "Functional impairments in DRAM1 are associated with the pathogenesis of several degenerative diseases, notably glaucoma and diabetic retinopathy." (PMID 40771354, 2025).
E. coli infection (1 paper, 2023). "Consistently, our findings demonstrate that upregulation of DRAM1 was involved in regulating autophagy and glycolysis in C10_ULK1 cells in response to both E. coli infection and E. coli sepsis." (PMID 37919720, 2023). "In Escherichia coli (E. coli) sepsis, 19 signature genes involved in epigenetic regulation and metabolism were identified, of which DRAM1 was demonstrated to promote autophagy and glycolysis in response to E. coli infection." (PMID 37919720, 2023). "Therefore, we believed that the relationship between DRAM1 and E. coli sepsis is related to the upregulation of autophagy in C10_ULK1." (PMID 37919720, 2023). "Together, our findings suggest that DRAM1 induced by ELF1 could upregulate autophagy to resist bacterial infection and promote glycolysis (presumably through its association with GAPDH) for autophagic energy supply during E. coli infection." (PMID 37919720, 2023). "Of particular note, DRAM1, a signature DEG in E. coli infection, was identified as unique to E. coli sepsis, further emphasizing the critical role of DRAM1 in E. coli-induced immune cell dysregulation." (PMID 37919720, 2023).
Fuchs corneal endothelial dystrophy (1 paper, 2023).
hearing loss (1 paper, 2022). "Three autophagy-related genes (Dram1, Fkbp1b, and Fos) were differentially expressed in the mild hearing loss group, whereas five autophagy-related genes (Dram1, Fkbp1b, Fos, Capn2, and Eef2) were differentially expressed in the severe hearing loss group." (PMID 35463035, 2022).
idiopathic pulmonary fibrosis (1 paper, 2022). Idiopathic pulmonary fibrosis (IPF) is a nonneoplastic pulmonary disease that is characterized by the formation of scar tissue within the lungs in the absence of any known cause. "DNA damage-regulated autophagy modulator 1 (DRAM1) has been known to act as a tumor suppressor in NSCLC, and miR-524-5p has been reported to be a biomarker in idiopathic pulmonary fibrosis and different lung disorders." (PMID 35222643, 2022).
Immunodeficiency (1 paper, 2023). Failure of the immune system to protect the body adequately from infection, due to the absence or insufficiency of some component process or substance. "Therefore, we conclude that Dram1 can compensate for (combined) deficiencies in the xenophagy pathway but not for general immunodeficiency." (PMID 38264729, 2023). "Thus, although Dram1 enhances the immune response to Mm infection in the absence of Optn or p62, it cannot compensate for general immunodeficiency caused by disruption of Myd88-dependent innate immune signaling." (PMID 38264729, 2023).
inflammatory bowel disease (1 paper, 2024). A spectrum of small and large bowel inflammatory diseases of unknown etiology. "In this regard, DNA Damage-Regulated Autophagy Modulator 1 (DRAM1) plays an important role in regulating autophagy and apoptosis and influences the pathogenesis of diseases such as inflammatory bowel disease (IBD)." (PMID 39195222, 2024).
leukemia (1 paper, 2019). A malignant (clonal) hematologic disorder, involving hematopoietic stem cells and characterized by the presence of primitive or atypical myeloid or lymphoid cells in the bone marrow and the blood. "Moreover, the CCK-8 cell proliferation assay indicated that K562/ADM cell viability was remarkably reduced by 15–20% upon ADM treatment compared with the siNC group, indicating DRAM1 suppression exerted important functions in improving drug resistance in leukemia cells." (PMID 31636666, 2019). "However, in the present study, to determine whether DRAM1 influenced leukemia cells autophagy and ADM resistance, K562/ADM cells expressing a relatively higher level of DRAM1 were selected for siRNA-mediated knockdown." (PMID 31636666, 2019).
myocardial ischemia (1 paper, 2024). A disorder of cardiac function caused by insufficient blood flow to the muscle tissue of the heart. "DRAM1 showed a significant direct interaction only with Atg7, which regulated the autophagic flow of DRAM1-Atg7-Atg12/Atg5 under the stress condition of myocardial ischemia, thereby alleviating autophagic flow and regulating the mechanism of myocardial cell protection." (PMID 38414735, 2024).
osteoporosis (1 paper, 2025). A condition of reduced bone mass, with decreased cortical thickness and a decrease in the number and size of the trabeculae of cancellous bone (but normal chemical composition), resulting in increased fracture incidence. "This study identified PDPK1, MAP1LC3B, ZFP36, DRAM1, and MPO as potential biomarkers and proposes a nomogram based on hub genes for predicting osteoporosis risk." (PMID 39791175, 2025). "Similarly, DRAM1 (damage-regulated autophagy modulator 1), another autophagy-related gene, affects osteoporosis by promoting autophagy and influencing osteoblast function." (PMID 39791175, 2025).
osteosarcoma (1 paper, 2018). A usually aggressive malignant bone-forming mesenchymal neoplasm, predominantly affecting adolescents and young adults.
prostate carcinoma (1 paper, 2012). A carcinoma that arises from epithelial cells of the prostate gland. "Cumulatively, pro-apoptotic genes, such as XAF1 and GADD45B were down-regulated, whereas DRAM1 was up-regulated in the adipose tissue of prostate cancer patients." (PMID 23009291, 2012).
Sepsis (1 paper, 2023). Sepsis is defined as life-threatening organ dysfunction caused by a dysregulated host response to infection. "We speculate that activation of DRAM1 may upregulate autophagy to counter bacterial infection, leading to expansion of C10_ULK1 cells in sepsis." (PMID 37919720, 2023). "DRAM1 upregulation was confirmed in an independent sepsis cohort." (PMID 37919720, 2023).
squamous cell carcinoma (1 paper, 2019). A carcinoma arising from squamous epithelial cells. "Specifically, DRAM1 mRNA was downregulated in squamous cell carcinoma (SCC) of head and neck tumor samples, which highlight the important role of DRAM1 in epithelial cancers." (PMID 30902093, 2019).
tumor (33 papers, 2012 to 2025). "DRAM1 also recruited Bax to lysosomes and caused the release of cathepsin B to initiate Bid-mediated apoptosis of tumor cells under stress conditions." (PMID 32943616, 2020). "In our analysis, we showed that DRAM1 was associated with a good prognostic value, suggesting that the expression of DRAM1 in malignant cells could inhibit tumor growth." (PMID 35884522, 2022). "By fusing BioID2 to DRAM1, they successfully identified key interacting partners contributing to DRAM1’s tumor suppressor role." (PMID 39857961, 2025). "For validation of our predicted tumor suppressor role of DRAM1 in the ATscore, we used siRNA to inhibited the expression of DRAM1 in A549 and H1299 cells." (PMID 35529878, 2022). "Further research showed that the amount of Am in tRNAs was significantly related to the expression of FTSJ1, which exerted significant tumor suppressor ability via interacting with DNA damage-regulated autophagy modulator 1 (DRAM1)." (PMID 34660690, 2021). "Compared with normal lung tissues, the intensity of DRAM1 immunoreactivity was decreased in tumor tissues." (PMID 32943616, 2020). "The present work uncovered a novel mechanism of the tumor suppression by DRAM1: promoting EGFR endosomal-lysosomal trafficking and degradation in NSCLC in vitro and in vivo through interacting with EPS15 and promoting the assembly of lysosomal v-ATPase." (PMID 32943616, 2020). "GEO database and Oncomine database were utilized to analyze the differential expression of DRAM1 in normal lung and tumor tissues." (PMID 32943616, 2020). "Compared with control tumors, overexpression of DRAM1 inhibited PC9 tumor growth with a significant reduction in tumor growth rate, tumor size and weight." (PMID 32943616, 2020). "DRAM1 potentially suppresses tumor development, and its mRNA levels are reduced in many types of cancer." (PMID 30344951, 2018). "In our signature A, only DRAM1 was preferentially expressed by tumor cells." (PMID 35884522, 2022). "DRAM1 has been found to play a tumor suppressor role in NSCLC." (PMID 35222643, 2022). "We showed that the tumor suppressive effect of FTSJ1 on NSCLC was partially mediated by DRAM1." (PMID 32393790, 2020). "In addition, rescue assays demonstrated that the tumor suppressive effect of FTSJ1 depended on DRAM1 expression, as co-transfection of FTSJ1 and si-DRAM1 into NSCLC cells significantly enhanced the tumor suppressive effect of FTSJ1 on cell proliferation." (PMID 32393790, 2020). "Collectively, multiple lines of evidence indicated that FTSJ1 may exert a tumor suppressor function partly through interacting with DRAM1 in NSCLC." (PMID 32393790, 2020). "DRAM1 also increased the tumor inhibition of gefitinib in vivo." (PMID 32943616, 2020). "Furthermore, the pivotal role of rpS6 phosphorylation in tumor formation is consistent with our observation that DRAM1 inhibits rpS6 phosphorylation and act as a tumor suppressor." (PMID 30902093, 2019). "The previous study identified DRAM1 as a potential tumor-suppressor in human cancer." (PMID 30902093, 2019). "The downregulation of DRAM1 in tumor cells is the result of hypermethylation within CpG islands in its promoter region, as well as other mechanisms, such as the epigenetic modification of core histones near the DRAM1 gene." (PMID 30344951, 2018).
tumor (continued). "However, the mechanisms by which DRAM1 inhibits tumor growth are not fully understood." (PMID 32943616, 2020). "DNA damage-regulated autophagy modulator 1 (DRAM1) plays an important roles in autophagy and tumor progression." (PMID 32943616, 2020). "Moreover, DNA damage-regulated autophagy modulator 1 (DRAM1) plays an important role in autophagy and tumor progression." (PMID 37925175, 2023). "Expression of two lysosomal components CTSD (cathepsin D) and DRAM1 (damage-regulated autophagy modulator 1) was significantly up-regulated in both FL and DLBCL tissue biopsies, suggesting they may be expressed at higher levels in the tumor microenvironment." (PMID 25362242, 2014).
cancer (31 papers, 2011 to 2024). A tumor composed of atypical neoplastic, often pleomorphic cells that invade other tissues. "The lysosomal protein DRAM1/Dram1 regulates autophagy and cell survival/death decisions under multiple stress conditions, including diseases like cancer and infection." (PMID 32332700, 2020). "DRAM1 and other members of the DRAM family have been linked to cancer, myocardial infarction, HIV infection, and TB, but their molecular and cellular functions remain poorly understood." (PMID 32332700, 2020). "Further studies to thoroughly elucidate the role of DRAM1 in tumorigenesis will help to design new strategies for cancer therapy." (PMID 30902093, 2019). "Our discovery of DRAM1 inhibited rpS6 phosphorylation via the PI3K-Akt-mTORC1-rpS6 pathway provided a mechanistic possibility for understanding the role of DRAM1 in human cancer." (PMID 30902093, 2019). "DRAM1 was initially described as regulating autophagy in cancer; here, we extended its role in the context of cerebral I/R." (PMID 25342320, 2014). "DRAM1 primarily localizes to lysosomes and is frequently downregulated in various human cancers." (PMID 38203743, 2024). "In vivo, the mice in the model groups displayed cancer progression, and the expression of some of the autophagy-related genes, DRAM1, NBR1, ATG7, MAP1LC3A were also increased in mice given F. nucleatum or F. nucleatum with L-cysteine when compared to the untreated control mice." (PMID 37889013, 2023). "DRAM1 induces autophagy and is downregulated in a variety of human cancers." (PMID 36276869, 2022). "Emerging evidence suggested that DRAM1 is engaged in the biological functions of cancer cells." (PMID 35222643, 2022). "To investigate whether DRAM1 could inhibit the phosphorylation of rpS6 in human cancer cell lines, we overexpressed DRAM1 in human cancer cells." (PMID 30902093, 2019). "Finally, DRAM1 decreased cell viability upon serum starvation and inhibited rpS6 phosphorylation in human cancer cells." (PMID 30902093, 2019). "DRAM1 has also been reported to be dysregulated in several human cancers." (PMID 30902093, 2019). "We believe that rpS6 phosphorylation could serve as the starting point to elucidate the functions of DRAM1 and its role in human cancer." (PMID 30902093, 2019). "Our results that DRAM1 inhibits PI3K-Akt-mTOR pathway might bridges these two isolated phenomena observed in SCC together and provide a new clue for the potential mechanism underlying the tumorigenesis of this type of human cancer." (PMID 30902093, 2019). "Additionally, DRAM1 inhibited rpS6 phosphorylation in several human cancer cells." (PMID 30902093, 2019). "Thus, our results identify that the class I PI3K-Akt-rpS6 pathway is regulated by DRAM1 and may provide new insight into the potential role of DRAM1 in human cancers." (PMID 30902093, 2019). "The eight mRNAs selected for further analysis, AXL, SCG5, VOPP1, DCBLD2 and DRAM1 are cancer-promoting genes, DUSP1, AQP5 and BLNK are cancer suppressor genes." (PMID 37925175, 2023). "The results revealed five cancer-promoting genes (AXL, SCG5, VOPP1, DCBLD2, DRAM1), and three tumor suppressor genes (DUSP1, AQP5, BLNK)." (PMID 37925175, 2023). "DNA damage-regulated autophagy modulator 1 (DRAM1) is known to induce autophagy and is downregulated in multiple human cancers." (PMID 35222643, 2022).
cancer (continued). "In the presence of growth factors, DRAM1 regulates the activation of the IGF-1 receptor and inhibits the downstream PI3K-AKT-mTOR pathway, promoting autophagy activation and suppressing cell proliferation in various human cancers." (PMID 35222643, 2022). "Although DRAM1 alone fails to induce programmed cell death under physiological conditions, DRAM1-induced autophagy is involved in stimulator-induced apoptosis, where it exerts either a positive or a negative impact on survival of cancer cells." (PMID 32943616, 2020). "Interestingly, several genes, such as DRAM1, SERPINE2, SDC2 and CTSB, have been shown to correlate with chemotherapy efficiency in cancers 20-24." (PMID 31660072, 2019). "We also demonstrated that DRAM1 regulated the activation of the IGF-1 receptor and inhibited the downstream PI3K–AKT–mTOR pathway in the presence of growth factors, resulting in autophagy activation and decreased cell proliferation in several human cancer cells." (PMID 32943616, 2020).